INS (insulin)
Diseases named in the same sentence as INS in open-access papers (continued):
Sharing a sentence is not in itself a finding about the gene and the disease.
diabetes (continued). "When comparing the endocrinologist to IM cohorts (43,693 vs. 43,693), the endocrinologist cohort also had significantly higher frequency of all types of testing, prescription of insulin (0.4 times/month), and diabetes-related costs (USD 430 more)." (PMID 35330461, 2022). "Diabetes mellitus (DM) is a chronic disorder marked by raised blood glucose levels due to disruption in the secretion of insulin, or its utilization or both." (PMID 35050096, 2022). "Diabetes mellitus (DM) is defined by persistent hyperglycemia and impaired carbohydrate, lipid, and protein metabolism as a result of total or partial insulin secretion or action." (PMID 35197747, 2022). "Metformin is an oral insulin-sensitizing agent, considered the first line treatment in type 2 diabetes mellitus." (PMID 36009471, 2022). "Teens generally understood that diabetes is a condition that affects blood sugar and insulin, that there are different types of diabetes, that diabetes can be inherited, and that diabetes can be related to being overweight." (PMID 35955010, 2022). "The proportion of patients with a diabetes duration of > 5 years was higher in patients with mental disorders, as was that of those prescribed insulin or ≥ 3 oral hypoglycemic agents." (PMID 36397079, 2022). "The importance of the gut microenvironment for maintaining physiological levels of glucose and insulin has been validated in the streptozotocin (STZ)-induced diabetes model in mice by adjuvant therapy with Sacha inchi (Plukenetia volubilis L.)tea." (PMID 35454311, 2022). "Shepherd and Kahn demonstrated that the plasma FFAs levels of patients with obesity and diabetes are elevated because of the abnormal release of insulin-resistant adipocytes." (PMID 36364926, 2022). "Any deficit of insulin or a decreased tissue response to insulin action impairs glucose, lipid and protein metabolism and leads to chronic hyperglycemia and diabetes." (PMID 36246880, 2022). "The glucagon level and fasting serum insulin were evaluated in all groups after 12-week diabetes treatment and induction." (PMID 35211170, 2022). "One of the first examples of islet encapsulation to treat diabetes was transferring human insulin-secreting tissue with a membranous bag into rats in 1933." (PMID 35903090, 2022). "The median time since diagnosis of diabetes was 14.5 years (range: 0.5–36 years), and 8 participants were receiving insulin treatment." (PMID 36374930, 2022). "Diet management plays an essential role, supporting the insulin treatment, in the prevention of diabetes complications through inflammation pathways modulation and cardiovascular risk reduction." (PMID 36562032, 2022). "Diabetes can be induced by high doses of PI3K inhibitors because the pathway is involved in insulin signaling." (PMID 36354662, 2022). "Type 1 diabetes mellitus is an autoimmune disease characterized by the failure of the pancreatic cells to secrete any insulin and leads to a severe increase in blood glucose levels, causing long-term complications." (PMID 35431983, 2022). "Suicide prevention strategies should focus on insulin-dependent diabetics with a history of depression, particularly for those with access to rapid-acting insulin." (PMID 35943711, 2022). "Since the revelation of insulin nearly a century ago, undoubtedly, there have been prominent efforts made in understanding diabetes." (PMID 35600597, 2022). "Stem cell therapy is a promising approach for diabetes via promoting the differentiation of insulin-producing cells (IPCs)." (PMID 35395037, 2022). "As expected, main diabetes-specific data (BMI, HbA1c levels, fasting glucose, insulin level, and HOMA-index, etc.)differed significantly between the control and T2DM groups." (PMID 36421383, 2022). "Insulininjektionstherapie, Menschen mit Typ-1-Diabetes substituieren das fehlende Hormon Insulin durch eine Form der Insulintherapie." (PMID 35294561, 2022).
diabetes (continued). "The outcome variable ‘EM-Diabetes availability’ was calculated as a counting score of the tracer medicines: metformin, glibenclamide, injectable insulin, and injectable glucose solution." (PMID 35317808, 2022). "The models can predict the 12- and 36-month risk of PDAC with moderate accuracy among male veterans initiating insulin for diabetes and male veterans with increasing A1c levels." (PMID 34728468, 2022). "During hospitalization, all T2D patients received diabetes treatment, either only oral medication, oral medication plus insulin, or only insulin." (PMID 35047039, 2022). "Sensitive analyses showed consistent results after adjusting for previous diabetes mellitus, oral hypoglycemic agents and insulin injection." (PMID 36699024, 2022). "The basis of the metabolic abnormalities in carbohydrate, fat, and protein in diabetes is insufficient action of insulin on various target tissues." (PMID 35711333, 2022). "Type 2 diabetes mellitus (T2DM) is a metabolic disorder characterized by hyperglycemia resulting from insulin resistance or reduced insulin secretion." (PMID 36514747, 2022). "The way services were structured had an influence on how people managed their diabetes with insulin." (PMID 35983585, 2022). "For instance, increased insulin sensitivity, reduced serum glucose levels, hypometabolism of cerebral glucose, and low chances of occurrence of type 2 diabetes mellitus have been found in NF1 individuals." (PMID 36064430, 2022). "Todd Zio, an Massachusetts Institute of Technology expert, launched a firm named SmartCells Inc. in 2003, quickly receiving support from Juvenile Diabetes Research Foundation as it attempted to create GRI (glucose-responsive insulin)." (PMID 36381916, 2022). "A lack of understanding about diabetes, or inadequate access to diabetes education, was a barrier to managing diabetes with insulin." (PMID 35983585, 2022). "In particular, comorbid diabetes has been shown to propagate IL‐6 and INS gene expression, leading to increased ACE2 via NAD‐dependent histone deacetylase Sirtuin." (PMID 35644866, 2022). "Studies of human islets have shown reduced glucose-dependent insulin secretion in type 2 diabetes mellitus even when allowance is made for the reduction in insulin content." (PMID 35453469, 2022). "Diabetes mellitus is a set of metabolic disorders marked by hyperglycemia due toa defect in insulin secretion or insulin action or both." (PMID 35877423, 2022). "By week 10 in the diabetes reversal arm of the experiments, the triple therapy (A+B+C) group had fewer mice dependent on insulin therapy compared with all other groups." (PMID 36339443, 2022). "Today, current guidelines concerning diabetes management of AHF patients propose that insulin-based glycaemic control should be considered in cases of hyperglycaemia (>10 mmol/L or >180 mg/dL) with the target adapted to possible comorbidities." (PMID 35329874, 2022). "A characteristic feature of exogenous insulin used in the treatment of diabetes is its therapeutic index." (PMID 35324747, 2022). "Reduced insulin signaling in aging and diabetes hinders muscle protein synthesis (MPS) and promotes muscle protein degradation, leading to loss of muscle mass and eventually sarcopenia." (PMID 36482911, 2022). "Diabetes mellitus is a group of endocrine and metabolic disorders characterised by insufficient insulin secretion to maintain the right blood glucose level." (PMID 35663309, 2022). "Diabetes mellitus is a group of chronic metabolic disorders characterized by a high blood sugar level (hyperglycemia), which results from abnormalities in either insulin secretion or action." (PMID 36011665, 2022). "ROS affects multiple signaling pathways, leading to compromised insulin secretion, insulin resistance, and β-cell dysfunction in diabetes." (PMID 36632095, 2022).
diabetes (continued). "Diabetes mellitus (DM) is a metabolic disease characterized by high levels of blood glucose due to the effect of impaired insulin utilization, abnormal insulin secretion, or both." (PMID 36547210, 2022). "They improve insulin response, preserve functionality and survival of β-cells and protect against diabetes complications." (PMID 35276982, 2022). "Studies have revealed that melatonin improved aberrant glucose metabolism and decreased insulin secretion in diabetes." (PMID 35668933, 2022). "During last few decades, inhibition of glucagon secretion or its action to improve insulin sensitivity and decrease insulin resistance is one of numerous therapeutic approaches to treat type 2 diabetes mellitus." (PMID 36307866, 2022). "Administration of esculetin at 40 mg/kg was reported to reduce blood glucose levels and increase plasma insulin levels in streptozotocin (STZ)-induced diabetes in male albino rats." (PMID 36293500, 2022). "These are present in approximately 50–80% of patients with diabetes receiving exogenous insulin with lower incidence in T2D patients compared to T1D patients." (PMID 35742925, 2022). "Methionine restriction attenuates glucose homeostasis, insulin sensitivity, oxidative stress, inflammation in diabetes, and this evidence highlights the idea that methionine is a potential contributor to the pathogenesis of diabetes." (PMID 36014850, 2022). "Diabetes is a multifaceted disorder that occurs in glucose use and insulin-related metabolic processes." (PMID 34174798, 2022). "The regulation of insulin secretion from pancreatic β cells represents yet another context-specific function elicited by islet-expressed Lphns with potential repercussions on diabetes, a metabolic condition which is also comorbid with ADHD." (PMID 35393556, 2022). "Type 1 diabetes mellitus and diabetes after total pancreatectomy completely deplete insulin secretion." (PMID 35992127, 2022). "The genetic background of diabetes development differs between Japanese and European people, and Japanese patients with type 2 diabetes are less likely to have impaired insulin secretion and are less likely to be obese than Europeans." (PMID 36078917, 2022). "Diabetes involves complex physiological changes, which include dysregulated hepatic glucose production, inadequate insulin secretion, and peripheral IR." (PMID 35458669, 2022). "Curcumin and prebiotic Lactobacillus acidophilus were co-delivered for the treatment of insulin resistant experimental animals with diabetes." (PMID 35807304, 2022). "The drug history was insulin for diabetes, antihypertensive medicines and mofetil, mycophenolate, prednisolone, and cyclosporine for kidney transplantation." (PMID 35872680, 2022). "Numerous studies have explored the role of periodontitis in the incidence of diabetes in animal investigations and have shown that oral administration of periodontal bacteria diminished glucose tolerance and insulin sensitivity in mice." (PMID 36299624, 2022). "MCP-1 expression is induced by insulin and plays a role in diabetes because of impaired glucose metabolism." (PMID 36428998, 2022). "In Type 1 diabetes mellitus (T1DM), the immune destruction of pancreatic beta cells leads to deficient production of insulin and renders patients dependent on life-long exogenous insulin therapy." (PMID 35497883, 2022). "Diabetes mellitus (DM) is a metabolic disease marked by excessively high blood glucose levels because of insufficient endogenous insulin production or activity." (PMID 35624887, 2022). "Diabetes is a chronic condition characterized by persistently high levels of glucose in blood due to insufficient insulin action or secretion." (PMID 35957811, 2022). "The general conclusion of this meta-analysis is that resveratrol has a significant dose-response effect on glucose concentrations, HbA1c percentage and insulin levels in subjects with type 2 diabetes mellitus, aged 45–59 years." (PMID 36687699, 2022).
diabetes (continued). "AYAs with T1D most often asked healthcare professionals (physicians, diabetes educators, and dietitians) about information related to insulin and BGM." (PMID 38515508, 2022). "Intradermal insulin delivery techniques using a hollow microneedle have been studied in children and adolescents with type 1 diabetes mellitus." (PMID 35890301, 2022). "Since the era of the first closed-loop systems in the 1960s and ‘70s, progress in diabetes management has been closely tied to advances in diabetes technology with the proliferation of devices for continuous insulin delivery and glucose monitoring." (PMID 35733769, 2022). "Most of these data, however, derive from cohorts with type 2 diabetes, diabetes of unspecified type, or, rarely, insulin-treated versus non-insulin-treated diabetes, whereas information on type 1 diabetes is notably lacking." (PMID 36068573, 2022). "This study suggests that improved access and affordability of insulin and diabetes supplies is needed to reduce the financial burden and prevent adverse outcomes among PWD." (PMID 36562281, 2022). "Persistent hyperglycemia decreases the sensitivity of insulin‐sensitive organs to insulin, owing to which cells fail to take up and utilize glucose, which exacerbates the progression of type 2 diabetes mellitus (T2DM)." (PMID 35184403, 2022). "Studies also indicate a more severe course of COVID-19 in patients with diabetes mellitus and lower effectiveness of insulin treatment." (PMID 35453807, 2022). "Diabetes refers to conditions where the body is either incapable of producing enough insulin or of using the insulin that is produced." (PMID 35890880, 2022). "The implementation of diabetes was achieved with STZ by damaging insulin producing β cells of pancreatic islets." (PMID 36071445, 2022). "The diagnosis of prediabetes or diabetes mellitus often relies on fasting glucose and insulin measurements, or on glycated hemoglobin (HbA1c) values, without paying heed to glucose dynamics." (PMID 35271177, 2022). "The predictors for a higher LDL-C trend are younger adults, Malay and Indian ethnicities, females, dyslipidemia, and diabetes treatment with lifestyle modification and insulin." (PMID 36317122, 2022). "Recently, HDAC inhibitors have been found to improve insulin resistance in peripheral tissues, thereby reducing inflammation and improving and delaying diabetes complications." (PMID 35433838, 2022). "It induces a significant weight loss and an improvement in lipid parameters, blood pressure, glycaemic indices and insulin sensitivity in patients with obesity and type 2 diabetes mellitus." (PMID 35745118, 2022). "More research is necessary to understand the specific rationales for seeking crowdfunding for diabetes care, such as insulin therapy, and to understand if crowdfunding is a successful solution for increasing insulin access." (PMID 35436214, 2022). "The traditional diabetes treatment medications mainly focus on insulin secretion and sensitization, which brings adverse side effects to patients, resulting in drug treatment incompliance and failure." (PMID 35855056, 2022). "The present therapeutic options used for treatment of NAFLD patients with diabetes include insulin sensitizing agents such as metformin and thiazolidinediones." (PMID 36072931, 2022). "In our recently published study, lower physical activity, higher adiposity markers, and diabetic-related parameters (HbA1c %, insulin) were shown to be significantly correlated with fatigue scores in patients with type 2 diabetes mellitus (T2DM)." (PMID 35600795, 2022). "In exploratory animal models, M. charantia has shown encouraging impacts in preventing diabetes mellitus and retarding the advancement of diabetic complications, including neuropathy, gastroparesis, nephropathy, waterfall, and insulin obstruction." (PMID 35434401, 2022).
diabetes (continued). "For instance, the common drugs used to treat diabetes, such as insulin and metformin, have been shown to be effective in stimulating the release of NO and maintaining vascular stability." (PMID 36117707, 2022). "Compared to white individuals, South Asians tend to have a faster increase in FBG, quicker decline in insulin sensitivity, and more marked disturbance in beta-cell compensation before diabetes diagnosis." (PMID 35464070, 2022). "Insulin pens have changed the lives of millions of people who suffer from diabetes and now are the most widespread way of administering insulin." (PMID 35355552, 2022). "Many participants with a long duration of diabetes conditions told the interviewer that they were familiar with insulin therapy and that they knew how to tackle blood glucose fluctuations." (PMID 35250851, 2022). "The development of drugs targeting the relevant signaling pathway of PDX-1 in insulin regulation will play a key role in treating diabetes; however, most related studies are animal experiments in the exploratory stage." (PMID 36551213, 2022). "It is well-known that pancreatic β-cells secrete insulin and insufficient insulin secretion triggers diabetes." (PMID 35813288, 2022). "Controlling the blood glucose by lifestyle intervention and the administration of hypoglycemic drugs and insulin can effectively prevent the occurrence and postpone the development of diabetes." (PMID 36295827, 2022). "Diabetes mellitus is a chronic metabolic disorder characterized by hyperglycemia due to inadequate insulin secretion, insulin resistance, or both." (PMID 36185927, 2022). "Diabetes is a chronic systemic disease with a complex pathogenesis characterized by peripheral insulin resistance, abnormal regulation of hepatic glucose production and decreased beta-cell function, which ultimately leads to beta-cell failure." (PMID 37092111, 2022). "Oxidative stress and aberrant insulin signaling transduction play vital roles in type 2 diabetes mellitus (T2DM)." (PMID 35153796, 2022). "Diabetes mellitus is an endocrine disorder that affects glucose metabolism, making the body unable to effectively use the insulin it produces." (PMID 36557487, 2022). "QoL consists of cognitive and emotional components (e.g., satisfaction and happiness) and multiple factors modify QoL in patients with diabetes, including medication adherence, disease duration, depression, insulin use, and the presence of comorbidities." (PMID 35895728, 2022). "The indications for PTA were as follows: brittle diabetes (n = 15; 83.34% out of 18), rapid progression of microangiopathic complications (n = 2; 11.11%), and severe insulin therapy-related emotional problems in one patient." (PMID 35566547, 2022). "For example, one mother with diabetes was forced to go back to the maternity ward because it was time for her to take her insulin." (PMID 35067210, 2022). "Since the kidney is a relevant site for glucose and insulin metabolism, glycemic control is particularly challenging in ESRD patients with diabetes, owing to a higher risk of hypo and hyperglycemia." (PMID 35657123, 2022). "It is primarily divided into Type 1 diabetes mellitus (T1DM), which occurs due to absolute deficiency in insulin secretion caused by autoimmune destruction of pancreatic beta cells (β-cells)." (PMID 36339446, 2022). "Because insulin directly stimulates GnRH secretory activity, hyperglycemia occurs bydecreased insulin secretion in diabetes." (PMID 36273315, 2022). "After the discovery of insulin, nutrition has become central in the management of diabetes in order to limit glycemic rise after meals, optimize metabolic control, and prevent complications." (PMID 36432570, 2022). "Protein tyrosine phosphatase 1B (PTP1B), a negative regulator of the insulin signaling pathway, has gained attention as a validated druggable target in the management of type 2 diabetes mellitus (T2DM)." (PMID 35782627, 2022).